IHO1 (interactor of HORMAD1 1)
Description:
Required for DNA double-strand breaks (DSBs) formation in unsynapsed regions during meiotic recombination. Probably acts by forming a complex with MEI4 and REC114, which activates DSBs formation in unsynapsed regions, an essential step to ensure completion of synapsis. Not required for HORMAD1 functions in pairing-independent synaptonemal complex formation, ATR recruitment to unsynapsed axes, meiotic silencing of unsynapsed chromatin (MSUC) or meiotic surveillance.
Synonyms: CT74; CCDC36; FLJ25320; LELA1
Tractability: PROTAC: ubiquitination databases record sites on it.
Gene: Protein-coding gene on chromosome 3 (49,198,428 to 49,258,106, forward strand). Ensembl gene ENSG00000173421.
Subcellular location: Chromosome
Subcellular location (Human Protein Atlas): Nucleoplasm
Gene Ontology:
Molecular function: protein binding
Biological process: homologous chromosome pairing at meiosis; meiotic DNA double-strand break formation; oogenesis; regulation of homologous chromosome segregation; spermatogenesis; DNA recombination
Cellular component: chromosome; condensed nuclear chromosome
Genetic constraint (gnomAD): Loss-of-function variants: 6 observed, 20.16 expected, observed/expected ratio (o/e) 0.3, 90% interval 0.16 to 0.59. The upper end of that interval is the gene's LOEUF score, 0.59, which puts it in group 2 of 6, group 1 being the genes least tolerant of losing a copy. Missense variants: 558 observed, 672.48 expected, observed/expected ratio (o/e) 0.83, 90% interval 0.77 to 0.89. Synonymous variants: 207 observed, 248.42 expected, observed/expected ratio (o/e) 0.83, 90% interval 0.74 to 0.94.
Homologues: Orthologues: chimpanzee IHO1 (98% identical), macaque IHO1 (94% identical), pig IHO1 (74% identical), dog IHO1 (73% identical), rabbit IHO1 (72% identical), guinea pig IHO1 (63% identical), rat Iho1 (56% identical), mouse Iho1 (55% identical), tropical clawed frog iho1 (25% identical), zebrafish ccdc36 (21% identical).
Diseases named in the same sentence as IHO1 in open-access papers:
IHO1 is named in the same sentence as 3 diseases in open-access papers, as found by Europe PMC text mining. Sharing a sentence is not in itself a finding about the gene and the disease.
IHO1 shares sentences with these, for which no sentence is quoted: cancer (1 paper); depression (1); Infertility (1).